ACKR3 (atypical chemokine receptor 3)
Diseases named in the same sentence as ACKR3 in open-access papers (continued):
Sharing a sentence is not in itself a finding about the gene and the disease.
cancer (continued). "A continuously growing number of publications report elevated ACKR3 expression in many human cancers, including solid tumors and hematological malignancies." (PMID 29156704, 2017). "The atypical chemokine receptor 3 (ACKR3) is important for cell migration in development and cancer." (PMID 28098154, 2017). "Co-expression of CXCR4 and ACKR3 has been reported both on separate cells and on the same cells within primary cancers." (PMID 29088715, 2017). "Alongside cancer-related pathways, several enriched pathways related to aging and neurodegenerative diseases, such as cellular senescence and autophagy were identified as ACKR3 miRNA targets." (PMID 40667070, 2025). "We propose a chemokine-independent role for ACKR3 in basal motility of cancer cells." (PMID 41330916, 2025). "Moreover, previous studies have implicated ACKR3, CHAF1B, CHEK1, and COL11A1 as being involved in cancer cell proliferation, while CA9, CHAF1B, and COL11A1 play roles in cancer invasion and migration." (PMID 38652547, 2024). "In the case of ACKR3, the finding that RAMPs can diminish receptor internalization and ligand scavenging presents a valuable opportunity to stabilize this interaction as a novel therapeutic strategy for pain management and against cancer." (PMID 39662834, 2024). "CXCR4, its ligand CXCL12 and the atypical receptor ACKR3 are overexpressed in many human cancers." (PMID 36713377, 2022). "We showed that atypical chemokine receptor 3 (ACKR3), a receptor of the CXC motif chemokine 12 (CXCL12) implicated in cancer, inflammation, and cardiovascular disorders, is selectively expressed on the surface of senescent human fibroblasts but not on proliferating cells." (PMID 35742971, 2022). "Nevertheless, this study establishes a previously unknown function of CXCL12 signaling to regulate PKM2 and glucose metabolism, connecting CXCR4 and ACKR3 to the metabolic adaptations of cancer cells." (PMID 35681470, 2022). "In addition to inflammatory models, the impact of ACKR3 on trans-endothelial migration is reported to be important in cancer studies as well, as this process allows malignant cells to metastasize." (PMID 35674847, 2022). "Future research will determine the extent to which the CXCL12-dependent regulation of PKM2 through CXCR4 or ACKR3, either alone or in combination, controls the metabolic states of cancer cells relative to other downstream effectors, with established effects on the metabolism." (PMID 35681470, 2022). "Significantly, ACKR3 is a well-known OG, present in Tier 1 of the Cancer Gene Census." (PMID 33427197, 2021). "ACKR3 plays an important role in cancer and vascular diseases." (PMID 33799570, 2021). "In addition, ACKR3 knockout using the crispr/cas9 method andS100A4knockdownusing targeted shRNA exerted additive effects suppressing cancer cell proliferation and migration." (PMID 31895690, 2019). "Interestingly, both cancer and endothelial cells express the atypical receptor ACKR3/CXCR7 that regulates cell invasion, adhesion and angiogenesis, through the activation of the Akt-dependent pathway." (PMID 30591657, 2018). "Overall, the emerging scenario suggests that the relative expression levels of CXCR4 and ACKR3 and whether they are expressed in the same or distinct subpopulations of cancer or stromal cells, may have an impact on CXCL12-mediated responses, highlighting a relevant question for future research." (PMID 36233192, 2022). "Furthermore, its critical role in shaping CXCL12 gradients suggests that ACKR3 inhibition could have major effects on both cancer and immune cell trafficking." (PMID 35159113, 2022). "Furthermore, it was recently discovered that the atypical chemokine receptor ACKR3 is also upregulated in many cancers, including breast; however, reports are contradictory on whether ACKR3 expression is pro- or anti-metastatic." (PMID 30441765, 2018).
cancer (continued). "The interaction between the CXCL12/CXCR4/ACKR3 axis and the STAT3 signaling pathway is crucial in the development and progression of various diseases, including cancer." (PMID 38920657, 2024). "Other notable proteins, such as ACKR3, COL11A1, CPA4, and FZD6, were previously reported as potential therapeutic targets in cancer." (PMID 38652547, 2024). "So far, only small molecules, peptides, modified chemokines and antibody fragments targeting ACKR3 have been reported, partly owing to the long-established importance of the CXCR4–CXCL12 axis in cancer, autoimmune and cardiovascular diseases." (PMID 37153591, 2023). "Scavenging of CXCL12 by ACKR3 has also been shown to promote growth and metastasis of CXCR4+ breast cancer cells and is thought to contribute to the progression of other cancers." (PMID 35857509, 2022). "ACKR3, along with CXCR4, with which it shares a ligand, CXCL12, plays an important role in cancer progression." (PMID 33799570, 2021). "The known roles of VEGFA, ACKR3, IL6 and FYN establish them as the major regulators of cancer pathways cluster in the network." (PMID 34439877, 2021). "ACKR3, previously known as CXCR7, is the alternate receptor of the inflammatory chemokine CXCL12, and several studies have unveiled the importance of this chemokine receptor axis in cancer as well as cardiometabolic diseases." (PMID 33917642, 2021). "However, thus far, ACKR3 expression and function in postnatal lymphatic vessels have not been investigated, but could be important considering that ACKR3 is currently under investigation as a drug target in cancer therapy." (PMID 33857173, 2021). "CXCR7, recently termed as atypical chemokine receptor 3 (ACKR3), is amongst the G protein coupled cell surface receptor family that is also commonly expressed in a large variety of cancer cells." (PMID 34298991, 2021). "Since the discovery of ACKR3 as a CXCL12-binding chemokine receptor in addition to CXCR4, its role in several cancers has been explored but its effects are still the source of many conflicting reports." (PMID 30441765, 2018). "ACKR3, in turn, increases the expression of pro-angiogenic factors such as IL-8 and VEGF and supports transendothelial migration of cancer cells." (PMID 30591657, 2018). "VEGF-A is highly expressed in macrophages and in cancer cells, and may induce MGP and atypical chemokine receptor ACKR3, which is a receptor of CXCL12." (PMID 41249124, 2025). "Basal non-chemotactic, cancer cell motility was also suppressed, suggesting a role for ACKR3 in this process." (PMID 41330916, 2025). "Understanding the relationship between the CXCL12/CXCR4/ACKR3 axis and the STAT3 pathway could lead to new therapeutic targets for innovative cancer treatments." (PMID 38920657, 2024). "ACKR3 expression was also reported to be induced by Tax in T-cell lines, albeit its expression by ATLL cells was highly heterogeneous, with a proposed role in cancer cell survival." (PMID 35159113, 2022). "It is noteworthy in this respect, that the genes showing the strongest signals of negative selection include several plasma membrane receptor proteins (e.g. ACKR3, CCR2, CCR5, CX3CR1, TBXA2R) that cancer cells utilize to promote migration, invasion, and metastasis." (PMID 33427197, 2021). "ACKR3 is an atypical chemokine-like receptor that binds CXCL12 a ligand with critical roles in angiogenesis, development, inflammation, immune challenges, and cancer." (PMID 34583741, 2021). "A number of antagonists and inhibitors targeting the CXCL12/CXCR4/ACKR3 axis are being developed in cancer indications, mostly in non-brain tumor related cancers and not in combination with radiotherapy." (PMID 30813533, 2019). "However, this ligand also binds ACKR3, an atypical chemokine receptor that modulates CXCR4 functions and is overexpressed in multiple cancer types." (PMID 31507535, 2019).
cancer (continued). "Despite its over-expression in many cancer cell lines, the data presented suggests that ACKR3 does not have a role in chemotaxis but its presence can increase cell front velocity if co-expressed with CXCR4." (PMID 30441765, 2018). "ACKR3 is reported to contribute to cancer cell migration, but not due to activation by CXCL1223,67." (PMID 41330916, 2025). "Crosstalk between the CXCL12/CXCR4/ACKR3 axis and the STAT3 signaling pathway has been hypothesized on the basis of findings that both the CXCL12/CXCR4/ACKR3 axis and STAT3 signaling pathway are involved in the progression of several cancers." (PMID 38920657, 2024). "The attenuation of Gαi-dependent signalling by ACKR3 is somewhat not ideal for cancer treatment." (PMID 34060588, 2021). "Thus, ACKR3 ligands are considered promising drugs in the context of cancer and neuroinflammation yet mechanistic understanding of ACKR3 biology is incomplete, and the potential of ACKR3 as a therapeutic target has not been fully exploited." (PMID 34583741, 2021). "As a whole, it is therefore evident that, regardless of the exact mechanism leading to CXCL12/CXCR4/ACKR3 over-expression/stimulation in cancer, this axis plays multiple fundamental roles in cancer progression and as such, offers an important potential target for disease treatment." (PMID 30257500, 2018).
cardiovascular diseases (15 papers, 2016 to 2025). "Offering an innovative translational perspective, this review also discusses the advantages and challenges of utilizing ACKR3/CXCR7 as a potential anti-thrombotic strategy in platelet-associated cardiovascular disorders, particularly in coronary artery disease (CAD) patients post-MI." (PMID 35053329, 2022). "Receptors such as CXCR4, CXCR5, and ACKR3 not only direct B-cell trafficking but also influence their phenotype in cardiovascular disease." (PMID 40986007, 2025). "In recent years, the functional involvement of ACKR3/CXCR7 in cardiovascular disease has been delineated using a lineage-specific receptor deficient mouse lines." (PMID 35053329, 2022). "Therefore, it is essential to ascertain the therapeutic ‘time-window’ during which availability of ACKR3/CXCR7 is observed as a potential anti-platelet drug target in cardiovascular diseases, and to categorically define a dosage and treatment regimen." (PMID 35053329, 2022). "Platelet receptors ACKR3 and CXCR4 play a crucial role in a variety of cardiovascular diseases." (PMID 39373210, 2025).
infection (15 papers, 2011 to 2024). The state of being infected such as from the introduction of a foreign agent such as serum, vaccine, antigenic substance or organism. "The activation of the S100 signaling pathway, along with the upregulation of candidate receptors, ACKR3 and GPRC5A, are closely associated with acute inflammation caused by GPS infection." (PMID 39202454, 2024). "ACKR3 is upregulated in a variety of pathological conditions related to infection, inflammation, and ischemia." (PMID 31895690, 2019). "Up-regulation of ACKR3 expression and those of its ligands in response to hypoxia, inflammation or infection suggests that ACKR3 function may vary under these different pathologic conditions." (PMID 35846294, 2022). "Our data on LPS-induced ACKR3 amplification therefore propose an involvement of ACKR3 not only in autoimmune neuroinflammatory disorders, but also in infection-associated CNS diseases." (PMID 29792190, 2018). "Notably, the abundance of seven chemokines, such as C–C motif chemokine ligand 14 (CCL14), CCL20, CCL25, CCL5, C–X–C motif chemokine ligand 10 (CXCL10), CXCL14, and atypical chemokine receptor 3 (ACKR3), was significantly higher by infection in the R line of the TSF flock." (PMID 30678719, 2019). "Furthermore, our data may indicate a novel role for ACKR3, with an impact not limited to auto-inflammatory diseases, but extending to infection-related neuroinflammation as well." (PMID 29792190, 2018). "In contrast to WB trophozoite infection, ACKR3 is only differentially transcribed at 1.5 h during GS infection but not later." (PMID 35573800, 2022).
inflammation (5 papers, 2017 to 2023). Aberrant reaction of the microcirculation characterized by movement of fluid and leukocytes from the blood into extravascular tissues. "In an acute peritoneal inflammation model, ACKR3 inhibition reduced accumulation of polymorphonuclear granulocytes in the peritoneal fluid of mice along with a reduction in neutrophil infiltration into lungs and livers of the mice." (PMID 35674847, 2022). "Moreover, in an acute pulmonary inflammation murine model, inhibition of ACKR3 was shown to reduce NF-κB phosphorylation." (PMID 35674847, 2022).
hematological malignancies (4 papers, 2017 to 2025). "Beyond conferring survival advantages to malignant cells, the activated CXCL12/CXCR4/ACKR3 axis also enhances the invasiveness of hematological malignancies by regulating cell migration and conferring resistance to chemotherapy." (PMID 38920657, 2024).
metabolic disease (3 papers, 2021 to 2025). A congenital disorder (due to inherited enzyme abnormality) or acquired (due to failure of a metabolically important organ) disorder resulting from an abnormal metabolic process. "A potential candidate in the research of metabolic diseases is the atypical chemokine receptor 3 (ACKR3)." (PMID 33917642, 2021).
neurodegenerative disease (2 papers, 2018 to 2025). A disorder of the central nervous system characterized by gradual and progressive loss of neural tissue and neurologic function. "The predicted pathways for ACKR3 miRNA indicated that 9 of the top 25 significantly enriched pathways were associated with aging and neurodegenerative diseases." (PMID 40667070, 2025).
blood neoplasms (1 paper, 2022). "The atypical chemokine receptor ACKR3 is known to be upregulated on both solid cancers and blood neoplasms." (PMID 36713377, 2022).
infectious disease (1 paper, 2018). A disorder directly resulting from the presence and activity of a microbial, viral, or parasitic agent in humans. "Whereas, to date, ACKR3 has been adjudged a key role primarily in autoimmune neuroinflammatory disorders, our results suggest its additional involvement in infectious diseases of the CNS." (PMID 29792190, 2018).
ACKR3 also shares sentences with these, for which no sentence is quoted: colon carcinoma (18 papers); colorectal cancer (16); gastric cancer (14); lymph node metastasis (12); neuroblastoma (10); esophageal squamous cell carcinoma (7); rheumatoid arthritis (7); thyroid cancer (7); Sepsis (6); endometriosis (5); multiple myeloma (5); osteosarcoma (5); adenocarcinoma (4); brain tumor (4); endometrial cancer (4); head and neck cancer (4); head and neck squamous cell carcinoma (4); Hypertension (4); ischemic stroke (4); osteoarthritis (4); pancreatic adenocarcinoma (4); papillary thyroid carcinoma (4); acute kidney injury (3); acute myeloid leukemia (3); autism (3); Burkitt lymphoma (3); colitis (3); Ewing sarcoma (3); inflammatory bowel disease (3); liver cancer (3).
A further 124 diseases each share a sentence with ACKR3 in 3 papers or fewer.